GAGE12G (G antigen 12G)
Synonyms: GAGE-12G; OTTHUMG00000024148; AL4; CT4.7
Tractability: Antibody: the Human Protein Atlas places it where antibodies can reach.
Gene: Protein-coding gene on chromosome X (49,570,400 to 49,577,754, forward strand). Ensembl gene ENSG00000215269.
Subcellular location (Human Protein Atlas): Plasma membrane; Cytosol; Golgi apparatus
Gene Ontology:
Molecular function: protein binding
Homologues: Orthologues: chimpanzee GAGE10 (82% identical). Paralogues in human: GAGE12F (100% identical), GAGE12C (99% identical), GAGE12D (99% identical), GAGE12E (99% identical), GAGE1 (98% identical), GAGE12H (98% identical), GAGE12J (98% identical), GAGE13 (98% identical), GAGE2A (97% identical), GAGE2E (94% identical), GAGE10 (91% identical), PAGE1 (52% identical), and 10 more.
Diseases named in the same sentence as GAGE12G in open-access papers:
GAGE12G is named in the same sentence as 1 disease in open-access papers, as found by Europe PMC text mining. Sharing a sentence is not in itself a finding about the gene and the disease.
GAGE12G shares sentences with these, for which no sentence is quoted: neuroblastoma (1 paper).